DSG2 (desmoglein 2)
Diseases named in the same sentence as DSG2 in open-access papers (continued):
Sharing a sentence is not in itself a finding about the gene and the disease.
pemphigus (8 papers, 2010 to 2023). Pemphigus is a group of rare autoimmune diseases that cause blistering of the skin and mucous membranes (mouth, nose, throat, eyes, and genitals).This conditioncan occur at any age, but often strikes people in middle or older age. "Based on these observations, we speculated that in situations of compromised Dsg3-mediated cell adhesion, e.g., keratin-deficiency or pemphigus, Dsg2 may be capable of compensating for loss of intercellular adhesion." (PMID 33193387, 2020). "Taken together, the data support the hypothesis of an autoantibody-induced rescue mechanism based on Dsg2 upregulation and Dsg2-Dsg3 heterophilic interactions to ameliorate loss of intercellular adhesion in pemphigus." (PMID 33193387, 2020). "Taken together, the data demonstrate that Dsg2 undergoes heterophilic interactions with Dsg3, which may attenuate autoantibody-induced loss of keratinocyte adhesion in pemphigus." (PMID 33193387, 2020). "Protein overexpression of desmoglein 2 was observed in intact and lesional skin of patients with pemphigus compared to the skin of controls." (PMID 35058080, 2022). "Anti-desmoglein 1 and 3 autoantibodies justify acantholysis in pemphigus; however, the pathogenesis of anti-desmoglein 2 is hypothetical." (PMID 35058080, 2022). "Our data show an upregulation of Dsg2 in a human ex vivo pemphigus skin model and in pemphigus patient epidermis." (PMID 33193387, 2020). "Further, Dsg2 upregulation was present in a human ex vivo pemphigus model at membranes of cells bordering blisters suggesting that PV-IgG-induced loss of adhesion was causative for this phenomenon." (PMID 33193387, 2020). "Taken together, these data argue for a compensatory mechanism in pemphigus based on heterophilic Dsg2-Dsg3 interactions." (PMID 33193387, 2020). "Our previous study showed that compared to wild-type mice, ectopic expression of Dsg2 in the superficial epidermis rendered the Inv-Dsg2 transgenic mice more resistant to blister formation by pemphigus foliaceus IgG." (PMID 25785582, 2015). "The participation of Dsg2 is poorly studied in the pathogenesis of pemphigus." (PMID 35058080, 2022). "Ex vivo and patient data suggest that Dsg2 could contribute to pemphigus pathogenesis as a compensatory mechanism." (PMID 33193387, 2020). "Dsg2 was upregulated in PV patients’ biopsies and in a human ex vivo pemphigus skin model." (PMID 33193387, 2020). "In contrast, Dsg2 was reported to be upregulated in perilesional skin of pemphigus patients." (PMID 33193387, 2020). "Next, we analyzed Dsg2 expression in perilesional pemphigus patient samples." (PMID 33193387, 2020). "Here, we further generated a stable Dsg3-deficient cell line, which showed disturbed cell adhesion and upregulation of Dsg2 in the insoluble, desmosome-containing fraction supporting the observations revealed by immunostaining of ex vivo and pemphigus patient epidermis." (PMID 33193387, 2020). "Therefore, we analyzed the heterophilic Dsg2-Dsg3 interactions by cell-free AFM measurements after treatment with AK23, a pathogenic anti-Dsg3 antibody, derived from a pemphigus mouse model." (PMID 33193387, 2020). "To investigate whether Dsg2 upregulation is present in pemphigus lesions, we used a human ex vivo pemphigus skin model." (PMID 33193387, 2020). "Taken together, these data suggest that pemphigus autoantibodies induce Dsg2 upregulation." (PMID 33193387, 2020). "Our data confirm upregulation of Dsg2 in pemphigus patient skin." (PMID 33193387, 2020). "In contrast, increased bond lifetime of the heterophilic Dsg2-Dsg3 interactions may stabilize keratinocyte adhesion under conditions when Dsg3-mediated cell adhesion is disturbed by pemphigus autoantibodies." (PMID 33193387, 2020). "The impact of the Dsg2-CSTA influence on cell adhesion may play a yet unrecognized role in the skin fragility condition pemphigus." (PMID 25785582, 2015).
pemphigus (continued). "This hypothesis was confirmed by a transgenic mouse model in which increased Dsg2 levels limited superficial blister formation induced by the injection of pemphigus foliaceus (PF) antibodies targeting Dsg1 into neonatal mice." (PMID 23326495, 2013). "Autoantibodies against desmoglein 2 are not pathogenic in pemphigus; protein and gene overexpression of desmoglein 2 in the skin and mucosa may be involved in acantholysis repair." (PMID 35058080, 2022). "Therefore, we here examined the biophysical properties of heterophilic Dsg2-Dsg3 interactions and whether upregulation of Dsg2 affect pemphigus pathogenesis." (PMID 33193387, 2020). "Sheddases ADAM10 and ADAM17 are involved in the turnover of the desmosomal cadherin Dsg2 and ADAM10 has been shown to contribute to acantholysis in a murine pemphigus model." (PMID 35844545, 2022). "The present results allow the conclusion that autoantibodies against Dsg2 are not pathogenic in pemphigus and that protein and gene overexpression of Dsg2 in the skin and mucosal samples from patients with PF and PV may be involved in the protection against acantholysis." (PMID 35058080, 2022). "Thus, we wondered whether Dsg2 upregulation could serve as a compensatory mechanism in pemphigus." (PMID 33193387, 2020). "As for the first question, the analysis of the results points to the non-pathogenicity of anti-Dsg2 antibodies in pemphigus." (PMID 35058080, 2022). "We selected Dsg2 since it is not a pemphigus antigen and does not appear to have the consensus sequence required for cleavage by exfoliative toxins." (PMID 20631906, 2010). "Here, we applied a monoclonal Dsg2 antibody (mAb) targeting the extracellular domain which we have shown to be inhibitory in a previous study as well as AK23, an inhibitory monoclonal antibody from an active pemphigus mouse model targeting the Dsg3 adhesive interface." (PMID 23326495, 2013). "In this paper, we demonstrate that ectopic expression of Dsg2 in the superficial epidermis could limit both PF Ig- and ETA-induced skin blister formation, suggesting that steric hindrance plays a role in the mechanism of pemphigus." (PMID 20631906, 2010).
Ventricular arrhythmia (8 papers, 2021 to 2026). "Desmosomal (PKP2, DSG2), lamin (LMNA) and truncating FLNC variants destabilize the cytoskeleton, activate inflammatory and adipogenic programmes and shorten action-potential duration, changes that favor ventricular arrhythmias long before global LV dilatation." (PMID 40742635, 2025). "Patients are predisposed to a wide spectrum of clinical presentations, such as ventricular arrhythmia and SCD, which are associated with mutations in desmosome genes, such as plakoglobin (JUP), desmoplakin (DSP), plakophilin 2 (PKP2), desmoglein 2 (DSG2), and desmocollin 2 (DSC2)." (PMID 35433691, 2022). "Despite the presence of the DSG2 variant, there are no data for the presence of life-threatening ventricular arrhythmias and structural changes of the right ventricle (RV) in our patients." (PMID 34202524, 2021). "The patient lacking desmoglein-2 expression in heart tissues manifested recurrent and uncontrollable ventricular arrhythmia." (PMID 33949662, 2021).
dilated cardiomyopathy (7 papers, 2013 to 2025). Cardiomyopathy which is characterized by dilation and contractile dysfunction of the left and right ventricles. "In our case, the results even go beyond the anterior segment dysgenesis phenotype to highlight a potential life-threat to members of this family with the expression of a nonsense mutation in DSG2 within its members that could lead to dilated cardiomyopathy and sudden cardiac death." (PMID 28979898, 2017). "We examined plakophilin-2, desmoglein-2, desmocollin-2, plakoglobin and β-catenin protein expression levels from seven independent ARVD/C heart samples compared to two ischemic, five dilated cardiomyopathy and one healthy heart sample as controls." (PMID 24086444, 2013).
non-small cell lung carcinoma (7 papers, 2020 to 2026). A group of at least three distinct histological types of lung cancer, including non-small cell squamous cell carcinoma, adenocarcinoma, and large cell carcinoma. "It was demonstrated that DSG2 expression was increased in non-small cell lung cancer, skin carcinomas and human colon adenocarcinomas, implying a possible oncogenic function of DSG2 protein." (PMID 36016457, 2022). "Our results demonstrated that in non-small cell lung cancer (NSCLC), high DSG2 expression is associated with poor OS." (PMID 35345582, 2022).
basal cell carcinoma (6 papers, 2014 to 2021). A carcinoma involving the basal cells. "In addition, aberrant expression of Dsg3 is also reported in basal cell carcinoma (BCC) where its expression correlates with Dsg2 at the mRNA level but differ greatly at the protein level, with the loss of coordination of DSG2 and DSG3 expression and a reduction of DSG3 in BCC." (PMID 34206820, 2021). "A recent study showed that overexpression of DSG2 induced STAT3 phosphorylation and further increased Gli1 levels in basal cell carcinomas." (PMID 32095325, 2020).
lymph node metastasis (6 papers, 2020 to 2023). "DSG2 was associated with some clinicopathological factors in CC including differentiation, lymph node metastasis, distant metastasis and AJCC stage." (PMID 33407183, 2021). "DSG2 expression was associated with differentiation (P = 0.033), lymph node metastasis (P = 0.045), distant metastasis (P = 0.006) and AJCC stage (P < 0.001)." (PMID 33407183, 2021). "One study demonstrated that DSG2 expression was associated with tumor size, lymph node metastasis, and TNM (TNM staging system), as well as being a predictor of poor prognosis in LUAD." (PMID 33217893, 2020). "Univariate analysis indicated that poor OS in patients with CC was associated with low DSG2 expression (P < 0.001), tumor size (P < 0.001), lymph node metastasis (P < 0.001), distant metastasis (P < 0.001), AJCC stage (P < 0.001) and venous invasion (P < 0.001)." (PMID 33407183, 2021). "Higher DSG2 expression was positively associated lymph node metastasis (p = 0.040)." (PMID 32095325, 2020). "The results demonstrated that DSG2 was correlated with lymph node metastasis and TNM stage in digestive system cancer." (PMID 35345582, 2022). "High expression of DSG2 was positively associated with TNM stage, tumor size and lymph node metastasis." (PMID 32095325, 2020). "We found that high DSG2 expression was positively correlated with TNM stage, tumor size, lymph node metastasis and poor prognosis of LUAD patients." (PMID 32095325, 2020). "High expression of DSG2 was correlated with TNM stage, tumor size, and lymph node metastasis." (PMID 33217893, 2020). "Patients with lymph node metastasis exhibited higher DSG2 expression than patients without lymph node metastasis (0.113 ± 0.087 vs 0.053 ± 0.034, p = 0.014)." (PMID 32095325, 2020).
myocarditis (6 papers, 2016 to 2024). Myocarditis is a condition that is characterized by inflammation of the heart muscle (myocardium). "Our findings further advance the field of ACM, by demonstrating that an HFD further increases the circulating TC, potentiating cardiac dysfunction and myocardial inflammation, in the presence of the primary root cause (i.e., Dsg2-mutation)." (PMID 38999835, 2024). "A recent study reported variants in the DSP and DSG2 genes in six probands with familial myocarditis, allowing subsequent identification of up to 28 gene variant carriers, 39% of whom had a phenotype consistent with LV rather than classic right ventricular (RV) ACM." (PMID 37189393, 2023). "In addition, DSG2 variants have been recognized as pathogenic variants involved in biventricular impairments, and these variants also contribute to an overlapping manifestation with myocarditis." (PMID 37288269, 2023). "In this view, it is interesting to highlight the role of e.g. DSP, DSG2 and PKP2 mutations in acute (recurrent) myocarditis." (PMID 39347728, 2024). "As for ACM, pathogenic variants in desmosomal genes, namely plakoglobin (JUP), desmoplakin (DSP), plakophilin (PKP2), desmoglein (DSG2), and desmocollin (DSC), are depicted as the main cause, in turn displaying extensive overlap with myocarditis." (PMID 37189393, 2023). "As described in recent papers, the reactive nature of myocarditis in ARVD has been supported by the massive inflammatory cell infiltrates found after acute myocardial necrosis in early stages of disease in desmoglein-2 transgenic animal model." (PMID 27871237, 2016). "For the first time, anti-DSG2-abs were also assessed in myocarditis/DCM patients, which tested positive in 48% of cases; moreover, the anti-DSG2-ab titer was similar between ARVC and myocarditis/DCM patients." (PMID 39597880, 2024). "Further studies are warranted to provide external validation for anti-DSG2-ab assessment, explore a genotype–phenotype analysis, and to identify the full autoantigenic targets related to the AIDA IFL pattern observed in ARVC and myocarditis." (PMID 39597880, 2024). "Anti-DSG2-ab titer was not different between ARVC and myocarditis/DCM patients (48% anti-DSG-ab positive)." (PMID 39597880, 2024). "They found that anti-DSG2 autoantibodies (anti-DSG2-abs) were specific for ARVC and absent in healthy subjects and patients with other forms of heritable cardiomyopathy, but myocarditis patients were not included in the study." (PMID 39597880, 2024).
ovarian carcinoma (6 papers, 2020 to 2023). A malignant neoplasm originating from the surface ovarian epithelium. "Recently, primary ovarian cancer cells’ DSG2 immunohistochemistry signals and mRNA levels suggested DSG2 as a prognostic and diagnostic biomarker for ovarian cancer." (PMID 36016457, 2022). "This was recently illustrated by efficacy of a chimeric oncolytic Ad5/3 vector in ovarian cancer, which uses DSG-2 as its dominant entry receptor." (PMID 32957644, 2020). "In conclusion, these data showed that the dominant receptor for ONCOS‐102 binding and replication was DSG2 in these ovarian cancer cell lines." (PMID 31944306, 2020). "CD46 is often located within tight junctions and less accessible than DSG2 in many cells, including ovarian cancer." (PMID 31944306, 2020). "Moreover, patients with ovarian cancer with high serum levels of shed DSG2 had significantly shorter progression-free and overall survival than those with lower DSG2 levels." (PMID 35521959, 2022). "The vector, named ONCOS-102, demonstrated effective oncolysis of several ovarian cancer cell lines, while in the absence of DSG-2, despite the presence of CD46 and CAR, no oncolysis was observed." (PMID 32957644, 2020). "We speculate that patients with ovarian cancer expressing DSG2 may be more susceptible to the oncolytic activity of ONCOS‐102 and other oncolytic AD5/3 vectors than those with EOC without detectable DSG2 expression." (PMID 31944306, 2020).
pancreatic adenocarcinoma (6 papers, 2008 to 2025). "In pancreatic adenocarcinoma cells, silencing of DSG2 resulted in loss of cell cohesion and improved migration and invasion." (PMID 32095325, 2020). "Furthermore, desmoglein 2 silencing leads to loss of cell cohesion and increases migration and invasion of pancreatic adenocarcinoma cells." (PMID 31938048, 2020). "Recent studies indicated that DSG2 was downregulated in gastric, prostate and pancreatic adenocarcinomas, which suggested that DSG2 functions as a tumor suppressor." (PMID 36016457, 2022). "The levels of immunoreactive Dsg1 and Dsg2 were reduced in pancreatic adenocarcinomas compared with both normal pancreatic and chronic pancreatitis tissues." (PMID 19091121, 2008). "Using in vitro degradation assays, both Dsg1 and Dsg2 could be readily proteolyzed by hK7, which is overexpressed in pancreatic adenocarcinomas." (PMID 19091121, 2008). "Additionally, expression of KLK7 in the human pancreatic adenocarcinoma cell line BxPC-3 significantly increased the amount of soluble desmoglein 2 shed from the cell surface, which correlates with the in vitro degradation data." (PMID 19091121, 2008). "In this report we have shown that the levels of cell-surface resident Dsg1 and Dsg2 are reduced in pancreatic adenocarcinomas compared with normal and chronic pancreatitis tissues." (PMID 19091121, 2008).
glioma (5 papers, 2015 to 2024). A benign or malignant brain and spinal cord tumor that arises from glial cells (astrocytes, oligodendrocytes, ependymal cells). "This study confirmed that CEBPD promoted the expression of DSG2 by transcription in glioma cells, thereby promoting the capacities for migration, invasion, and VM in glioma cells." (PMID 32997416, 2020). "CEBPD overexpression promotes the transcriptional expression of DSG2, which in turn promotes the capacities for migration, invasion and VM in glioma cells." (PMID 32997416, 2020). "In conclusion, this study found that the UBE2I/PUM2/CEBPD/DSG2 played crucial roles in regulating glioma VM." (PMID 32997416, 2020). "In summary, this study first discovered the abnormal expression of UBE2I, CEBPD, PUM2, and DSG2 in glioma tissues and cells." (PMID 32997416, 2020). "The upregulation of CEBPD promotes the binding to the upstream promoter region of DSG2 gene, further upregulates the expression of DSG2, and finally promotes the development of glioma VM." (PMID 32997416, 2020). "Our experimental results showed abnormal expression of UBE2I, PUM2, CEBPD, and DSG2 in glioma cells." (PMID 32997416, 2020). "And we found that the CEBPD/DSG2 axis regulates the capacities for migration, invasion, and VM in glioma cells." (PMID 32997416, 2020). "CEBPD knockdown inhibited the transcriptional regulation of the DSG2, thereby inhibiting the capacities for migration, invasion, and VM in glioma cells." (PMID 32997416, 2020). "miRNA alteration could be used to target the processed Dsg2, given its importance in gene expression and its reported anti-glioma and anti-hepatocellular carcinoma activity." (PMID 38473864, 2024). "In this study, the expression of DSG2 was significantly increased in the tumor tissue of glioma patients compared with normal brain tissue by qRT‐PCR and western blot, and the expression in glioma U251 and U373 cells was significantly higher than that of HA cells." (PMID 32997416, 2020). "Analysis of a primary receptor for Ad5/3, Desmoglein 2 (DSG2), indicated that the receptor was expressed in U87, A172, and U251 cell lines; however, little to no levels of the receptor could be detected in the U138 and U105 glioma lines." (PMID 26689910, 2015). "This study found that the knockdown of UBE2I, CEBPD, and DSG2, and the overexpression of PUM2 in vitro all inhibited the capacities for migration, invasion, and VM in glioma cells." (PMID 32997416, 2020). "The purpose of this study is to clarify the SUMO2/3‐induced SUMOylation in glioma, as well as the expression and interaction of PUM2, CEBPD, and DSG2, and the role of these molecules in regulating VM of glioma." (PMID 32997416, 2020). "First in our study we measured expression of primary receptors (DSG2, CD46 and CAR) in glioma cells." (PMID 25738357, 2015). "The analysis here provides evidence of the importance of DSG2 in Ad5/3 oncolysis: the glioma lines U105 and U138 expressed little to no DSG2." (PMID 26689910, 2015). "However, the role of SUMO2/3, PUM2, CEBPD, and DSG2 in glioma VM has not been reported." (PMID 32997416, 2020).
hepatocellular carcinoma (5 papers, 2020 to 2024). A malignant tumor that arises from hepatocytes. "On the contrary, increased DSG2 expression may function as a promising marker for unfavorable prognosis of hepatocellular carcinoma." (PMID 32095325, 2020).